ARL13B (ARF like GTPase 13B)
Diseases named in the same sentence as ARL13B in open-access papers (continued):
Sharing a sentence is not in itself a finding about the gene and the disease.
glioma (6 papers, 2018 to 2023). A benign or malignant brain and spinal cord tumor that arises from glial cells (astrocytes, oligodendrocytes, ependymal cells). "Thus, while previous results may represent some types of gliomas, there may be an association of ARL13B and the cilium with other aggressive gliomas." (PMID 37830570, 2023). "Collectively, these data suggest that increasing functional ARL13B inside the cilium leads to the lengthening of glioma cilia and a distal tip accumulation of SMO that is independent of exogenous SHH exposure." (PMID 37830570, 2023). "Like other cell types, glioma cilia enrich ARL13B, a regulatory GTPase and GEF localized to the ciliary membrane and required for ciliary structural maintenance." (PMID 37830570, 2023). "We find that increasing ARL13B in glioma cilia stimulates ciliary elongation and an increase in SMO/GLI2 accumulation." (PMID 37830570, 2023). "The Cancer Genome Atlas (TCGA) data sets indicate that gliomas with high ARL13B and SMO mRNA expression correlate with shorter overall patient survival." (PMID 37830570, 2023). "Gliomas with increased ARL13B, SMO, and GLI2 expression are more aggressive, but the relationship to cilia is unclear." (PMID 37830570, 2023). "Because gliomas are notoriously heterogeneous tumors, future studies should determine if glioma stem cells with ARL13B+ cilia display different capacities for enriching or activating SMO and GLI." (PMID 37830570, 2023). "More recently, TMZ was shown to induce enhancer of zeste homologue 2 (EZH2) which targets the expression of ADP ribosylation factor 13b (ARL13B), a regulatory GTPase highly concentrated in glioma cilia, as an adaptive mechanism that promotes chemoresistance." (PMID 35359402, 2022). "Collectively, our data suggest that factors increasing ARL13B expression in glioma cells may promote both changes in ciliary membrane characteristics and IFT proteins, leading to the accumulation of drug-resistant SMO and GLI." (PMID 37830570, 2023). "Collectively, these data suggest that increasing functional ARL13B inside glioma cilia may additionally alter the retrograde transport mechanisms, promoting further SMO/GLI accumulation." (PMID 37830570, 2023). "We next examined the effects of increasing ARL13B on glioma cilia morphology and SMO localization." (PMID 37830570, 2023). "Future analyses of patient gliomas should determine whether IFT88 expression is proportionate to the number of ARL13B+ cilia in a tumor or dependent on the quantity of ARL13B within each cilium." (PMID 37830570, 2023). "If it does exist, it appears to dissociate at the distal tip, based on our immunolabeling of distal tip buds that appear strongly SMO- but weakly ARL13B-labeled, which would suggest other factors are present in the glioma ciliary tip to promote this dissociation." (PMID 37830570, 2023). "To test whether the antiproliferative effects of HDAC6 inhibitors are dependent on tumor cell cilia, we generated patient-derived glioma lines devoid of cilia through depletion of ciliogenesis genes ARL13B or KIF3A." (PMID 33915983, 2021). "We next examined whether the effects of HDAC6 inhibitors on glioma cilia extend to normal neural cell types that harbor aaTub+ and ARL13B+ cilia, such as radial glial cells and GFAP+ astrocytes." (PMID 33915983, 2021). "Dysregulated levels of Arl13b in glioma cells may have significant consequences on the SHH signaling pathway and tumor cell proliferation." (PMID 30410731, 2018). "Serum exposure has been reported to significantly elevate the levels of Arl13b and other ciliary components in conditioned media, and we observed the release of glioma cilia vesicles containing Arl13b:GFP in the presence of 5% serum containing known cellular growth factors." (PMID 30410731, 2018). "Thus, how these findings relate to glioma cells and whether the relationship between ARL13B and SMO is SHH-dependent remains unclear." (PMID 37830570, 2023).
glioma (continued). "Thus, if TTFields affects ARL13B or ARL13B+ cilia, the sensitivity of glioma cells to TMZ could be enhanced." (PMID 35359402, 2022). "Furthermore, our findings suggest that the intracellular levels of ARL13B might impact glioma growth." (PMID 30410731, 2018). "While there is a direct correlation between ARL13b expression and IFT88 expression in the TCGA for glioma, the nature of this relationship is unclear." (PMID 37830570, 2023). "However, glioma cell lines whose cilia overexpress WT but not guanine exchange factor-deficient ARL13B, display reduced INPP5e, a ciliary membrane component whose depletion may favor SMO/GLI2 enrichment." (PMID 37830570, 2023). "First, we transfected two different parental glioma cell lines (L0 and S7) with Flag-tagged SMO, which revealed that SMO localized along the axonemal length of endogenous ARL13B." (PMID 37830570, 2023). "Increasing ARL13B expression promotes the accumulation of both activated SMO and GLI2 in glioma cilia." (PMID 37830570, 2023). "We next asked if increasing ARL13B promotes and accelerates a flag-tagged form of SMO to glioma ciliary distal tips." (PMID 37830570, 2023). "In one of our GBM-patient-derived cell lines (L0) expressing Arl13b:GFP transgenes, we observed that glioma cells displayed elongated cilia, accumulation of SMO at their ciliary tips, and excision of their distal tips." (PMID 37830570, 2023). "Thus, the increase in SMO associated with Arl13b:GFP overexpression in the GBM clones, enrichment which was particularly prevalent in the ciliary tips, may constitute one of the mechanisms stimulating the release of ciliary vesicles in glioma cells." (PMID 30410731, 2018). "It is noteworthy that our analysis of the TCGA database revealed that higher expression levels of ARL13B and SMO in low-grade glioma correlate with shorter overall patient survival." (PMID 30410731, 2018). "Our goal was to try and distinguish whether ARL13B inside or outside of glioma cilia drives the ciliary changes in SMO, and whether ARL13B drives increases in activated ciliary SMO." (PMID 37830570, 2023). "After single or repeated TTFields exposure, we plated cells in serum for 4 days, fixed, and immunostained for ARL13B alone or combined with pericentriolar material 1 (PCM1), another protein that clusters around the basal body and centrioles in glioma cells, or OFD1." (PMID 35359402, 2022). "We also examined how TMZ alone versus TMZ plus TTFields affects ciliogenesis and proliferation on both ARL13B+ (ciliated) and ARL13B− (nonciliated) glioma cell lines characterized previously." (PMID 35359402, 2022). "Even though growth stimulation, Arl13b-mediated SMO upregulation, and F-actin may contribute to glioma ciliary excision, further studies are needed to elucidate the exact mechanisms involved in this process." (PMID 30410731, 2018). "Our previous findings implicated a relationship between ARL13B and SMO in glioma cells that may, in part, be independent of SHH." (PMID 37830570, 2023). "Alternatively, in glioma, ARL13B does not bind or promote SMO ciliary localization." (PMID 37830570, 2023). "Thus, ARL13B appears to play a key role in regulating GBM growth and maintaining glioma stem cells." (PMID 37830570, 2023). "Since 500-nM 738 reduced the proliferation of S7 parental glioma cells but not ARL13B-KO/cilia-depleted S7 cells, we examined whether this decreased proliferation was due to enhanced cell differentiation and whether this effect depended on cilia." (PMID 33915983, 2021). "Similarly, we reported that Arl13b overexpression promotes SMO localization to GBM cilia in the absence of SHH, and that high levels of ARL13B and SMO expression in the tumors of glioma and gastric tumor patients was positively correlated with shortened post-diagnosis survival in these patients." (PMID 30842728, 2019).
glioma (continued). "It is possible that even in the absence of the SHH ligand, glioma cells that fail to properly maintain specific intracellular levels of Arl13b may undergo abnormal activation of ciliary signaling through the upregulation of SMO into their cilium." (PMID 30410731, 2018). "However, this phenomenon is not observed in glioma cells depleted of ARL13B." (PMID 37830570, 2023). "However, we do not know whether the ARL13B-mediated changes in the glioma cilia length or the SMO distribution are attributable to ARL13B’s ciliary or cellular role." (PMID 37830570, 2023). "The relationship between ARL13B, SMO, and GLI2 may be independent of SHH expression in glioma." (PMID 37830570, 2023).
breast carcinoma (3 papers, 2019 to 2020). "We observed that ARL13B mRNA expression levels are increased in more invasive tumors, being statistically significantly elevated in grade II, when compared with grade I breast carcinomas or the paired adjacent tissues." (PMID 31569511, 2019). "Since we established Arl13b as a positive regulator of breast cancer cell migration and invasion in vitro, we investigated if Arl13b plays a role in breast tumorigenesis in vivo, using a murine orthotopic model of breast cancer." (PMID 31569511, 2019). "In this study, we describe a new role for ARL13B as an oncogene in breast cancer progression and provide a possible mechanism by which this GTP-binding protein regulates cancer cell migration and invasion." (PMID 31569511, 2019). "We investigated the role of the ADP-ribosylation factor (Arf)-like (Arl) protein Arl13b in breast cancer cell migration and invasion in vitro, using breast cancer cell lines and in vivo, using mouse orthotopic models." (PMID 31569511, 2019). "To further ascertain the relevance of Arl13b in breast cancer progression, we assessed ARL13B mRNA and protein expression levels in different breast cancer cell lines with distinct invasive capacities." (PMID 31569511, 2019). "Next, we tested the effect of Arl13b overexpression in breast cancer cell migration and invasion and observed that it enhances both migration and invasion of MDA-MB-231 cells." (PMID 31569511, 2019). "We show that Arl13b silencing inhibits breast cancer cell migration and invasion in vitro, as well as cancer progression in vivo." (PMID 31569511, 2019). "We observed that Arl13b silencing impairs breast cancer cell migration and invasion in vitro and tumor growth and metastasis in vivo." (PMID 31569511, 2019). "Together, our results suggest that Arl13b is subverted by breast carcinomas, which upregulate its expression to become more migratory and invasive." (PMID 31569511, 2019). "Together, our results indicate that Arl13b positively regulates breast cancer cell migration and invasion in vitro." (PMID 31569511, 2019). "We found that the weakly invasive breast cancer cell lines BT-474 and MCF-7, and the highly invasive cell line MDA-MB-231, express significantly higher levels of ARL13B mRNA when compared with the in situ breast cancer cell line MCF10DCIS.com." (PMID 31569511, 2019). "Strikingly, by analyzing breast cancer tissue samples, we found that Arl13b is upregulated in breast carcinomas when compared with the expression in adjacent normal breast tissues." (PMID 31569511, 2019). "A similar effect in cell migration was observed when we overexpressed Arl13b in the weakly invasive MCF-7 breast cancer cell line." (PMID 31569511, 2019). "This was confirmed with different breast carcinoma samples and normal breast tissue derived from mammary reduction, as well as a different anti-Arl13b antibody." (PMID 31569511, 2019). "For this, freshly-collected breast carcinoma samples and their paired adjacent normal tissues were analyzed by RT-qPCR for ARL13B mRNA expression." (PMID 31569511, 2019). "Our results suggest a role for Arl13b in breast cancer progression by coordinating actin remodeling and cell-ECM adhesion during cancer cell migration and invasion." (PMID 31569511, 2019). "Indeed, depletion of ARL13B in breast cancer cells leads to a reduction in cell migration and invasion in vitro and impaired tumor progression in vivo." (PMID 32426352, 2020). "Our group also found that GTP-bound ARL13B interacts with NMIIA in breast cancer cells." (PMID 32426352, 2020). "Importantly, breast cancer is the third type of cancer whose progression or formation has been shown to be promoted by Arl13b and we also have evidence that the same occurs in colon cancer (our unpublished results)." (PMID 31569511, 2019). "Indeed, we observed colocalization of endogenous Arl13b with actin in structures such as lamellipodia, filopodia, SFs and CDRs of breast cancer cells." (PMID 31569511, 2019).
breast carcinoma (continued). "Thus, our study reinforces previous evidence for the involvement of Arl13b in cancer and suggests that Arl13b is subverted by breast cancer cells to become more motile and invasive, with potential to be targeted for therapeutic purposes." (PMID 31569511, 2019). "Here, we provide evidence that Arl13b positively regulates breast cancer progression." (PMID 31569511, 2019). "To investigate the mechanism by which Arl13b promotes cell migration and invasion and knowing that Arl13b interacts with actin, we evaluated its involvement in actin cytoskeleton remodeling in breast cancer cells." (PMID 31569511, 2019). "Therefore, Arl13b expression levels positively correlate with the invasive capacity of breast cancer cells." (PMID 31569511, 2019). "Therefore, we uncover a role for Arl13b in breast cancer cell migration and invasion and provide a new mechanism for how ARL13B can function as an oncogene, through the modulation of integrin-mediated signaling." (PMID 31569511, 2019). "We also observed that Arl13b is upregulated in breast cancer cell lines and patient tissue samples." (PMID 31569511, 2019). "In contrast, mice injected with Arl13b-overexpressing breast cancer cells develop large tumors." (PMID 31569511, 2019). "Interestingly, we observed that Arl13b interacts with NMIIA in a GTP-dependent manner in breast cancer cells." (PMID 31569511, 2019). "Indeed, mice injected with Arl13b-depleted breast cancer cells hardly develop primary tumors and when they do, these are very small." (PMID 31569511, 2019). "Next, we examined whether the expression of Arl13b is modulated in tissue samples derived from breast cancer patients by comparing mRNA and protein levels in primary breast carcinomas and normal adjacent tissue samples." (PMID 31569511, 2019). "Additionally, the analysis of another dataset of frozen breast carcinoma samples and adjacent normal breast tissues by immunoblotting shows that Arl13b protein levels are statistically significantly upregulated in breast carcinomas, when compared to adjacent normal breast tissues." (PMID 31569511, 2019). "Furthermore, we show that Arl13b is upregulated in breast cancer cell lines and tissues." (PMID 31569511, 2019). "Now, we confirmed that NMIIA interacts with Arl13b in MCF-7 and MDA-MB-231 breast cancer cells preferentially when the cell lysates are loaded with GTPγS, a non-hydrolysable form of GTP, as compared with excess GDP." (PMID 31569511, 2019). "Thus, our results suggest that Arl13b negatively regulates NMIIA expression and SF formation, therefore affecting FA growth in breast cancer cells." (PMID 31569511, 2019).
cyst (3 papers, 2017 to 2019). A sac-like closed membranous structure that may be empty or contain fluid or amorphous material. "However, it is unclear if irregular cilia morphology is a consequence or cause of cyst formation, and what function overexpression of Arl13b-EGFP in combination with polycystin-1 or polycystin-2 ablation may have in maintaining normal cilia length." (PMID 29443690, 2018). "Staining using antibodies against ARL13B and Acetylated α-Tubulin (Lys40) marking cilia, revealed multi-ciliated cells along the cyst lining." (PMID 30912742, 2019). "Using animals from the same study design, we harvested pIMCD cells from 2-month-old Arl13b-EGFPtg mice, before cyst development." (PMID 29443690, 2018). "Double labeling for acetylated α-tubulin and ciliary GTPase Arl13b showed that fragments within the cyst lumen were most likely ciliary structures, thus suggesting that these fragments of cilia had broken away from the apical surface of the cyst lining epithelial cells." (PMID 28487520, 2017).
gastric tumor (3 papers, 2018 to 2023). "The initial front loading of SMO into cilia may be related to reports on gastric tumor cells which state that ARL13B directly binds and stabilizes SMO." (PMID 37830570, 2023).
Kidney Cyst (2 papers, 2018 to 2023). Abnormal fluid filled sac within the kidney, either acquired or congenital. "In previous studies, we found that HDACIs could partially suppress kidney cyst formation and renal fibrosis caused by inactivation of polycystins or the cilia biogenesis gene Arl13b in model organisms." (PMID 36920028, 2023). "In our previous study, we found that inactivation of the cilia biogenesis gene Arl13b in mouse leads to kidney cysts and fibrosis." (PMID 36920028, 2023). "Consistent with previous reports from the cPkd2 and cPkd1 strain, we observed kidney cyst formation in Arl13b-EGFPtg:cPkd2 and Arl13b-EGFPtg:cPkd1 mice." (PMID 29443690, 2018). "To understand the putative ciliary ion channel function of polycystin-1 and/or polycystin-2, and to determine the effects of kidney cyst formation on cilia morphology, we crossed our Arl13b-EGFPtg strain with cPkd1 or cPkd2 mice (provided by S. Somlo Yale Univ)." (PMID 29443690, 2018).
retinal degeneration (2 papers, 2019 to 2021). Degeneration of the retina. "In humans, mutations in the ARL13B gene are associated with Joubert syndrome, an autosomal recessive ciliopathy characterized by multiple symptoms including retinal degeneration." (PMID 33681987, 2021). "Deletion of Arl13b in the mouse retina leads to mislocalization of rTα and rod PDE6 subunits but faster retinal degeneration than Arl3 deficiency does, suggesting additional functions of ARL13B other than a GEF for ARL3 in rod photoreceptor cells." (PMID 33681987, 2021). "To determine if heterozygous mutations in other cilia genes could exacerbate retinal degeneration, we bred cep290fh297/fh297 mutants to arl13b, ahi1, and cc2d2a mutant zebrafish lines." (PMID 30970040, 2019). "In this study, we evaluated the zebrafish cep290fh297/fh297 mutant in an effort to test ahi1, cc2d2a, and arl13b as potential genetic modifiers of retinal degeneration." (PMID 30970040, 2019).
Ataxia (1 paper, 2025). Ataxia refers to impaired coordination of voluntary muscle movement. "The affected female in this family had a more severe presentation of ataxia, which is a phenomenon previously reported, possibly due to increased ARL13B expression in the female brain compared to males." (PMID 40730687, 2025).
brain injury (1 paper, 2020). Acute and chronic (see also brain INJURIES, CHRONIC) injuries to the brain, including the cerebral hemispheres, CEREBELLUM, and brain STEM. "Moreover, Arl13b is also known to regulate the trafficking of Shh signaling components to primary cilia, elements known to have a role in reparations following brain injury." (PMID 32122360, 2020).
breast tumor (1 paper, 2019). "Collectively, these results indicate that Arl13b promotes both primary breast tumor formation and metastatic dissemination in vivo." (PMID 31569511, 2019). "We found that Arl13b overexpression leads to a significant increase in the size of breast tumors and abundant metastases in the lungs." (PMID 31569511, 2019).
cystic renal disease (1 paper, 2022). "This recessive hypomorphic allele was identified in a forward genetic screen in the mouse that caused rapid cystic renal disease and the analogous mutation in human TULP3, K389I, disrupted ciliary trafficking of ARL13B, GPR161, and INPP5E." (PMID 36276950, 2022).
Cystic renal dysplasia (1 paper, 2023). "We found that the expression of ARL13B was significantly decreased in the kidney of the proband with cystic renal dysplasia, and primary cilia were almost absent in the renal tubular epithelial cell of the proband." (PMID 37736303, 2023).